BCOR (BCL6 corepressor)
Diseases named in the same sentence as BCOR in open-access papers (continued):
Sharing a sentence is not in itself a finding about the gene and the disease.
neuroepithelial tumor (18 papers, 2017 to 2025). "We found a reported BCOR::CREBBP fusion in a neuroepithelial tumor with breakpoints in exon 4 of BCOR and exon 31 of CREBBP in the literature." (PMID 38637838, 2024). "High-grade neuroepithelial tumors with BCOR exon 15 internal tandem duplication (HGNET BCOR ex15 ITD) are rare pediatric tumors belonging to a discrete methylation class." (PMID 36604386, 2023). "Among the three samples classified historically as CNS-PNET, methylation profiling suggested the molecular diagnosis of the high-grade neuroepithelial tumor with BCOR alteration (HGNET-BCOR), ETMR, and ependymoma with RELA-fusion." (PMID 37835574, 2023). "ITDs involving exon 15 of the BCOR gene in a CNS neuroepithelioma and a renal tumor suggested revised diagnoses of high-grade neuroepithelial tumor with BCOR alteration and clear cell sarcoma of the kidney, respectively." (PMID 36585449, 2023). "Next, CNS high-grade neuroepithelial tumor with genetic alterations in either BCOR (HGNET-BCOR), FOXR1 (HGNET-FOXR1) or MN1 (HGNET-MN1) are newly described subtypes all characterized by distinct molecular alterations." (PMID 33260839, 2020). "Methylation class “CNS tumor with BCOR/BCOR(L1)-fusion” was recently defined based on methylation profiling and tSNE analysis of a series of 21 neuroepithelial tumors with predominant presence of a BCOR fusion and/or characteristic CNV breakpoints at chromosome 22q12.31 and chromosome Xp11.4." (PMID 38637838, 2024). "Methylation class “CNS tumor with BCOR/BCOR(L1)-fusion” was recently defined based on methylation profiling of a series of 21 neuroepithelial tumors with predominant presence of a BCOR fusion and/or characteristic CNV breakpoints at chromosome 22q12.31 and chromosome Xp11.4." (PMID 38637838, 2024). "A comparison study among methodologies showed that up to 10% of WNT medulloblastomas previously determined by nCounter were further classified as high-grade neuroepithelial tumor with BCOR alteration and anaplastic pilocytic astrocytoma by the DNA methylation assay." (PMID 37746264, 2023). "Here, the methylation classifier suggested a new entity, the methylation class neuroepithelial tumour with BCOR alteration, suggesting the diagnosis of a CNS tumour with BCOR internal tandem duplication, as well as two supratentorial ependymomas and one GBM of paediatric type." (PMID 35892159, 2022). "Central nervous system high-grade neuroepithelial tumor with BCOR alteration (CNS HGNET-BCOR) has been identified by methylome analysis in 2016 as a distinct molecular CNS tumor entity, which is characterized by an in-frame internal tandem duplication in exon 15 of the BCOR gene." (PMID 30526817, 2019).
myelodysplastic syndrome (17 papers, 2015 to 2026). A clonal hematopoietic disorder characterized by dysplasia and ineffective hematopoiesis in one or more of the hematopoietic cell lines. "The carriers of somatic PIGA and BCOR/BCORL1 mutations show a lower risk of AA transformation to myelodysplastic syndrome (MDS), whereas myeloid driver lesions such as DNMT3A and ASXL1 mutations characterize the group with a higher risk of malignancy." (PMID 38646536, 2024). "Recurrent somatic BCOR mutations have been identified in myelodysplastic syndrome (MDS)." (PMID 34461985, 2021). "BCL-6 co-repressor (BCOR) mutations occur in ~ 3–6% of AML, enriched in RUNX1-mutant or secondary AML following myelodysplastic syndromes." (PMID 41549155, 2026). "Mutations in U2AF1 and SRSF2 affect the spliceosome and are frequently found in antecedent hematological disorders, such as myelodysplastic syndrome (MDS) and myeloproliferative neoplasms (MPN), as well as are mutations in chromatin regulating genes ASXL1 and BCOR." (PMID 33509276, 2021). "In contrast, the TET2, FLT3, RUNX1, BCOR and spliceosome mutations were more common in the IDO1-high group, which were commonly enriched in myelodysplastic syndrome (MDS)-transformed AML." (PMID 40234305, 2025). "Cluster 1 was enriched with patients who had a prior diagnosis of myelodysplastic syndrome (MDS), mutations in the CSF3R gene, and mutations in the BCOR gene." (PMID 38232702, 2024).
Ewing sarcoma (16 papers, 2016 to 2025). A small round cell tumor that lacks morphologic, immunohistochemical, and electron microscopic evidence of neuroectodermal differentiation. "Recently, approximately 4% of the Ewing sarcoma were identified as having an intrachromosomal X-fusion leading to BCOR (encoding the BCL6co-repressor) and CCNB3 (encoding the testis-specific cyclin B3)." (PMID 27453756, 2016). "The expression of different markers such as BCOR and NKX2.2 implies a diagnostic conflict and overlap with other similar small round cell entities such as BCOR-altered neoplasms and Ewing sarcomas." (PMID 39062853, 2024).
leukemia (16 papers, 2014 to 2026). A malignant (clonal) hematologic disorder, involving hematopoietic stem cells and characterized by the presence of primitive or atypical myeloid or lymphoid cells in the bone marrow and the blood. "Subsequent studies will be needed to confirm HOX genes as target of BCOR mutations mediated in leukemia transformation of MDS." (PMID 34461985, 2021). "This study provides mechanistic understanding of how BCOR regulates cell fate decisions and how loss of function contributes to the development of leukaemia." (PMID 30902969, 2019). "Cancer-exome-sequencing endeavours have recently revealed that core components of the KDM2B/PRC1 complex, including KDM2B itself and BCOR/L1, are frequently mutated in a range of cancers, particularly leukemias." (PMID 24856970, 2014). "BCOR is required for myeloid differentiation and its deletion in mice disrupts H2AK119ub1-mediated repression of Hox genes during differentiation, leading to leukemia when paired with KRAS mutation." (PMID 34617019, 2021). "BCOR mutations occur more frequently in CN MDS patients, predicting higher risk of leukemia transformation." (PMID 34461985, 2021). "Here, the authors use mouse models to show the mechanism of how inactivation of BCOR in haematopoietic stem cells contributes to the development of leukaemia." (PMID 30902969, 2019). "To assess the relevance of the BcorΔE9-10KrasG12D murine model to human AML, we utilised two previously published mRNA expression data sets and analysed differential expression between BCOR-mutant (BCORMUT) and BCOR wild-type (BCORWT) leukaemia patients." (PMID 30902969, 2019). "Ten patients harbored alterations previously reported as somatically acquired variants, including in known leukemia genes (DNTM3A, TET2, and BCOR)." (PMID 28721364, 2015). "However, somatic mutations in the ncPRC1 subunit BCOR have been identified in AML and myelodysplastic syndrome, and mouse studies support a tumor suppressor function in leukemia." (PMID 31123059, 2019). "In MLL-rearranged leukemia, the MLL-AF9 fusion protein aberrantly recruits transcriptional and epigenetic modifiers, including DOT1L, BCOR, and CBX8, disrupting normal hematopoietic gene regulation." (PMID 42063817, 2026). "Some of these genes have been previously found to play important roles in haematopoiesis and leukaemia pathogenesis, e.g. PIM1, BCOR, TNFRSF8 and NR4A2." (PMID 26576536, 2015). "We identified and validated somatic mutations, often affecting known leukemia (DNTM3A, TET2, and BCOR) in tumor-infiltrating leukocytes but not in the cancer cells of 7 of the 15 patients." (PMID 28721364, 2015). "By contrast, all other tested somatic mutations detected in tumor-infiltrating leukocytes, including in known leukemia genes (DNMT3A, TET2, and BCOR) were not identified in breast cancer cells consistent with their origin in the leukocyte component." (PMID 28721364, 2015).
retinoblastoma (16 papers, 2013 to 2025). A malignant tumor that originates in the nuclear layer of the retina. "Of note, also in other embryonal tumors like retinoblastomas or medulloblastomas as well as in glial tumors mainly truncating loss-of-function BCOR mutations were reported." (PMID 41291966, 2025). "Other recurring changes include OTX2 amplification and BCOR mutations or loss, but they occur in a small minority of retinoblastomas." (PMID 37658463, 2023). "Given that BCOR gene function is associated with proper eye development, it seems plausible that inactivation of this gene can be related to retinoblastoma." (PMID 27126562, 2016). "The functional significance of BCOR mutations or MYCN amplifications is yet to be established in vivo in human retinoblastoma." (PMID 23765217, 2013). "The RB1 and BCOR (13%) genes are the only genes found to be recurrently mutated in human retinoblastomas to date." (PMID 23765217, 2013). "However, no alterations were encountered in recurrently mutated genes in RB1−/− retinoblastoma, such as BCOR or CREBBP." (PMID 32971811, 2020). "Therefore, BCOR deficiency enables retinoblastoma cells to survive under hypoxic conditions." (PMID 38920989, 2024). "Focal amplifications of the orthodenticle homeobox 2 gene (OTX2) were observed in 3% and focal deletions of the BCL6 Corepressor (BCOR) observed in 4% of the same cohort of retinoblastoma tumours." (PMID 33670346, 2021). "Taken together, our data suggest that MYCN and OTX2 are the most common focal gains found in retinoblastoma and RB1, and BCOR are the most common focal losses found in retinoblastoma." (PMID 24509483, 2014). "Genes such as BCOR, CREBBP, ATRX, SMARCB1, and ARID1A, which are involved in chromatin remodeling, transcriptional regulation, or DNA repair, have been found to be mutated or dysregulated in some retinoblastoma tumors." (PMID 41009976, 2025). "Moreover, a recent publication has identified a higher prevalence of SCNAs, as well as BCOR alternations, in retinoblastoma patients with extraocular disease, further implicating them as markers of a more aggressive disease." (PMID 33805427, 2021). "However, WGS allowed us to look at the full compendium of mutations in our cohort of retinoblastomas and suggests that driver mutations beyond RB1, MYCN BCOR and recurrent copy number changes on 1q, 2p, 6p, and 16q are rare." (PMID 33670346, 2021). "In addition to recurrent deletions in RB1, the most common focal deletions were in BCOR in 4% (4/94) of our retinoblastomas." (PMID 24509483, 2014). "Emerging genes beyond RB1 (e.g., BCOR, CREBBP) highlight the expanding genetic landscape of retinoblastoma." (PMID 41009976, 2025). "BCOR and CREBBP should be included, along with RB1, in any future targeted sequencing in order to maximise the capture of recurrent non-RB1 genetic variations within retinoblastoma patients." (PMID 33805427, 2021). "In addition to the previously reported recurrent focal losses of RB1 and BCOR and amplification of MYCN, we also identified a recurrent focal amplification of OTX2 in 3% of retinoblastomas." (PMID 24509483, 2014).
endometrial stromal sarcoma (14 papers, 2013 to 2025). "The identification of BCOR abnormalities in high-grade endometrial stromal sarcomas (ESSs) has transformed the diagnostic and prognostic landscape of this rare tumor." (PMID 39877469, 2025). "BCOR abnormalities are pivotal in the pathogenesis of high-grade endometrial stromal sarcomas (ESS), particularly in the ZC3H7B-BCOR gene fusion subtype, which is associated with aggressive clinical behavior, high recurrence rates, and poor outcomes." (PMID 39877469, 2025). "Additionally, endometrial stromal sarcomas with BCOR rearrangements usually exhibit MDM2 amplification and activation of the cyclin D1-CDK4 pathway." (PMID 40001568, 2025). "•BCOR abnormalities play a crucial role in high-grade endometrial stromal sarcomas." (PMID 39877469, 2025). "Moreover, high-grade endometrial stromal sarcomas are typically positive for cyclin D1, BCOR, and CD117/c-kit." (PMID 40150134, 2025). "However, the smooth muscle markers are positive in leiomyosarcoma, and BCOR is positive in high-grade endometrial stromal sarcoma." (PMID 35572973, 2022).
OFCD syndrome (12 papers, 2008 to 2025). "Mutations in BCOR cause oculofaciocardiodental syndrome, an X-linked dominant, male lethal condition that includes cardiac septal defects." (PMID 38378865, 2024). "The most well-characterized phenotype for pathogenic BCOR variants is OFCD syndrome, a dominant disorder with wide-ranging systemic effects." (PMID 38957147, 2024). "BCOR is a ubiquitously expressed protein, but two dramatically different syndromes arise from pathogenic variants in BCOR (BCL-6 corepressor): OFCD syndrome, which affects females, and a severe microphthalmia (“Lenz”-type) syndrome affecting primarily males." (PMID 38957147, 2024). "We diagnosed a Japanese girl with OFCD syndrome caused by a novel heterozygous frameshift variant in BCOR." (PMID 37308473, 2023). "OFCD syndrome has X-Linked dominant inheritance, which means that its effects are lethal in males, making all clinical patients females; BCOR gene abnormalities account for almost all cases of this syndrome." (PMID 35130870, 2022). "Here we report the case of a 3-month-old infant presenting with OFCD syndrome, and she experienced a heterozygous loss of exons 7–14 in the BCOR gene whereas both her parents presented with a normal genotype." (PMID 35130870, 2022). "Collectively, our findings suggest that BCOR mutation-induced ZFPM2 regulation via BCL6 possibly contributes to hyperactive root formation in OFCD syndrome." (PMID 35957990, 2022). "Evaluations of the genetic basis of OFCD syndrome have revealed truncating, missense, frameshift, and deletion mutations in the BCOR gene, all of which produce premature stop codons inducing varying OFCD syndrome phenotypes." (PMID 35130870, 2022). "The sporadic case #9 carried a novel BCOR mutation associated with OFCD syndrome, but she presented with only subtle clinical features, yet her cardiac status should be monitored for signs of disease progression." (PMID 29914532, 2018). "Syndromes associated with variants in BCOR include oculofaciocardiodental syndrome (OFCD) (a.k.a. syndromic microphthalmia type 2, OMIM# 300166), which is known to be associated with both OFC and TA." (PMID 27699475, 2016). "Germline BCOR mutations cause Oculofaciocardiodental syndrome, an inherited X-linked syndrome characterized by cardiac defects and dysmorphic appearance." (PMID 23577124, 2013). "OFCD syndrome is an X-linked dominant syndrome caused by a variety of BCOR null mutations." (PMID 38957147, 2024). "Oculofaciocardiodental syndrome is caused by variants in the BCL6 corepressor (BCOR) gene." (PMID 37308473, 2023). "However, the mechanism by which BCOR variants cause eye and other abnormalities in OFCD syndrome remains to be elucidated." (PMID 37308473, 2023). "Nonetheless, we found pathogenic mutations for specific developmental syndromes with CC and CHD as manifestations, including BCOR mutations for OFCD syndrome (DECIPHER ID 262217, 267974, and 303226), and the 11q21.1 deletion for 1q21.1 rearrangements of chromosome 1q21.1 (DECIPHER ID 323303)." (PMID 34059112, 2021). "CC with CHD is often reported in rare syndromes with well-defined genetic or chromosomal mutations or in syndromes resulting from intrauterine infection, such as OFCD syndrome caused by BCOR mutations, recurrent rearrangements of chromosome 1q21.1, Down's syndrome, and congenital rubella syndrome." (PMID 34059112, 2021). "Oculofaciocardiodental (OFCD) syndrome (MIM#300166), also called microphthalmia syndromic 2, is caused by variants in the BCL6 corepressor (BCOR) gene located at Xp11.4 and has male-lethal, X-linked, dominant inheritance." (PMID 37308473, 2023). "In patients with OFCD syndrome, BCOR regulates ZFPM2, which in turn regulates ALP expression during tooth root elongation." (PMID 35957990, 2022). "When we combined this with the clinical phenotype, it was easy to confirm a diagnosis of OFCD syndrome in this patient, likely as a result of the heterozygous deletion of exons 7–14 of the BCOR gene." (PMID 35130870, 2022).
OFCD syndrome (continued). "OFCD syndrome is caused by mutations in the B-cell lymphoma 6 (BCL6) interacting corepressor (BCOR) gene, which is located in the Xp11.4 region and encodes the BCL6 corepressor." (PMID 35957990, 2022). "Now named microphthalmia, syndromic 2 (MCOPS2, OMIM 300166), this syndrome is caused by mutations to the BCOR gene on Xp11.4." (PMID 18431456, 2008). "In the case of OFCD syndrome, disruption of the control of root length may be attributed to the activation of downstream molecules by the dysfunction of BCOR as a corepressor." (PMID 35957990, 2022). "In this study, we show that a BCOR mutation induced ZFPM2 regulation via BCL6, subsequently regulating ALP expression and cellular proliferation and possibly contributing to hyperactive root formation in the OFCD syndrome." (PMID 35957990, 2022). "A total RNA microarray revealed alterations in the expression of numerous genes in BCOR Mut PDL cells, several of which are implicated in transcriptional upregulation; NFIB, DLX5, and ZFPM2 were the most significantly upregulated genes in OFCD syndrome." (PMID 35957990, 2022). "Therefore, we investigated the gene expression profiles of PDL cells from patients with and without OFCD syndrome to identify the downstream components of the molecular mechanism by which BCOR regulates radiculomegaly in OFCD syndrome." (PMID 35957990, 2022). "Our findings suggest that BCOR failed to repress its downstream genes, resulting in elevated ZFPM2 and ALP expression and subsequent upregulation of cell proliferation, ultimately leading to hyperactive root formation in OFCD syndrome." (PMID 35957990, 2022).
glioma (11 papers, 2019 to 2025). A benign or malignant brain and spinal cord tumor that arises from glial cells (astrocytes, oligodendrocytes, ependymal cells). "EGFR, FAT4, and BCOR were the three features associated with 64% ACC using the TCGA-UCI glioma grading set aimed at tumor grading." (PMID 40362575, 2025). "EGFR, FAT4, and BCOR were the three features associated with 64% ACC using the TCGA glioma grading set." (PMID 40362575, 2025). "BCOR has also been linked to glioma via BCOR-altered gliomas, a newly identified glioma with a potential response to fluorinated pyrimidines, indicating that glioma formation in women may occur via different pathways in women and men, resulting in differential tumor responses to chemotherapy." (PMID 40362575, 2025). "The BCOR gene has been shown to be altered in a subset of pediatric tumors with embryonal features, as well as in pediatric gliomas." (PMID 37686092, 2023). "In addition to the most common glioma mutations, others were detected as PPM1D mutation (3 out 10 tested samples), PIK3CA mutation (2/10 tested), BCOR mutation (1/10 tested) and SETD2 mutation in 1/10 test SCA." (PMID 35267601, 2022). "Next-generation sequencing (NGS) of three cases identified mutations in a few genes known to be altered in low-grade gliomas, (e.g., BCOR, BCORL1, ERBB3, MYB, and ATM), but no recurrent mutations were seen." (PMID 31114608, 2019). "When employing the TCGA-UCI glioma grading dataset, the most discriminative and significant three features (63.6% ACC) are EGFR, FAT4, and BCOR." (PMID 40362575, 2025). "EP300–BCOR and BCOR–CREBBP have been described as potential oncogenic drivers in gliomas." (PMID 35169893, 2022).